IL5 (interleukin 5)
Diseases named in the same sentence as IL5 in open-access papers (continued):
Sharing a sentence is not in itself a finding about the gene and the disease.
Allergy (continued). "Contrary to what might have been predicted by the Th1-Th2 cytokine shift paradigm, infections with helminths result in a Th2-polarized immune response including production of IL-4, IL-5, IL-13, eosinophilia, and high serum titers of IgE, all hallmarks of allergic disease." (PMID 35648372, 2023). "At the same time, mouse serum OVA-sIgE, total IgE, IL-4, and IL-5 levels, along with H&E staining of nasal tissue, showed that gut microbiota dysbiosis dysregulates Th2 type allergic reaction and nasal inflammation in AR mice, which is consistent with previous studies of other allergic diseases." (PMID 36439824, 2022). "Therefore, the inhibition of Dectin-2-mediated inflammation may provide a robust approach for treating allergic diseases by simultaneously reducing IL-5 and IL-13 production." (PMID 31861989, 2019). "Apart from il5, expression of these gene transcripts was significantly reduced with GM-1111 treatment (p<0.001 to 0.05), suggesting that GM-1111 is effective in reducing key inflammatory cells and cytokines involved in allergy and Th2-mediated adaptive immune signaling." (PMID 30252910, 2018). "In experimental studies on different models of allergic diseases, gallic acid is demonstrated to suppress of allergen induced hypersensitivity reactions in mice and inhibit release of histamine and helper T cell subtypes, IL-4, IL-5 and IL-2 form human mast cells." (PMID 27536321, 2016). "Such increases in allergic diseases may be related to increased IL-5 and IL-10 levels." (PMID 27918476, 2016). "IL-4 along with IL-5 modulates eosinophil activation to stimulate B cells, IgE production, and mast cell degranulation and their reduction, has been shown in this study, could be involved in the modulation of symptoms of allergic disease." (PMID 25890178, 2015). "The role of Th17 cells and Th17 cytokines in allergic diseases is still unclear; however, some studies have indicated that Th17 cells may be involved in inhibiting the production of the Th2 cytokines, IL-4 and IL-5." (PMID 23346203, 2012). "In allergy-related cytokines, Fat only led to significant increases in multiple BALF cytokines, notably IL-4, IL-5, IL-6, IL-12, IL-13, IL-17, IL-33, TNF-α, and IFN-γ, compared to the normal chow group (NC) (all P < 0.05 or P < 0.01)." (PMID 40998975, 2025). "The results suggest that the body weight and thymus index returned to normal levels; allergy scores, serum OVA-sIgE, IL-4, IL-5, and IL-10 expression decreased; and IFN-γ and IL-2 increased significantly in the ZW3 group compared with the allergy group." (PMID 39796306, 2024). "Studies have shown that Th2-related cytokines such as IL-4, IL-5, and IL-13 can participate in the expression and secretion of mucin genes MUC5AC and MUC5B,29, 30, 31 further indicating the role of allergy in the occurrence and development of ETD." (PMID 38274710, 2024). "Surfacen® inhibited Th2 inflammation by lowering levels of IL‐5 and IL‐13 and increasing INF‐γ in bronchoalveolar lavage, decrease of serum specific IgE, increase of IgG2a antibody, suggesting potential anti‐allergy effects towards Th1‐immune response." (PMID 39245804, 2024). "Analysis of the drug treatment groups revealed lower levels of serum total IgE, OVA-specific IgE, and Th2 cytokines, including IL-4, IL-5, IL-13, IFN-γ, and eosinophils, compared to the allergy group." (PMID 38396957, 2024). "Cytokine recruitment, namely, IL-4, IL-5, IL-6, and TNF-α, encourages IgE synthesis in the first phases of an allergic reaction." (PMID 38835658, 2024). "A significantly smaller CD8+ iNKT cell population producing IFN-γ, IL-4, IL-5, and IL-10 in peanut-allergic adults was identified after exposure to DCs loaded with peanut oil, suggesting that despite a higher overall iNKT cell population, certain iNKT cell responses may be reduced in allergy." (PMID 38022648, 2023).
Allergy (continued). "In patients with allergies, the c9, t11 isomer of the CLA supplement for 12 weeks improved allergy symptoms and reduced some inflammatory factors (i.e., TNF- α and IL-5), while it increased IFN-γ levels." (PMID 37644566, 2023). "They function mainly in the mediation of allergic disease, parasitic as well as helminthic infections, and participate in type 2 (TH2) inflammation that involves key cytokines such as IL-4, IL-5, and IL-13." (PMID 36832203, 2023). "In our study, IL-5 was detected in all the blood samples, as well as in ALF, which can be interpreted as the expression of the Th2 cytokine allergic reaction." (PMID 36499410, 2022). "Interleukin (IL)-4, IL-5, and IL-13, mainly secreted by TH2 cells, are the critical stimulus that promotes serum IgE production and are crucial players in the development of allergic disease and wheezing." (PMID 34631611, 2021). "Other cytokines and chemokines such as IL-5, LIF, LIX, MCP-1, MIP-1a, and MIP-1b, which are believed to be involved in tissue damage, infection, and allergic diseases, also showed increased production in USA300 infections." (PMID 33573328, 2021). "C2, C9, IL5, SIGLEC15, and IL1RAP are examples of molecules with roles in immunity, inflammation and allergy that demonstrate seasonal effects." (PMID 33004787, 2020). "Therefore, licochalcone A significantly inhibited the expression of IL-5 in the airways and reduced the inflammation of tracheal epithelial cells, inhibiting eosinophil migration and infiltration in the lung tissue and reducing the allergy and peroxidation effect." (PMID 31226782, 2019). "In mouse and human allergies, IL-4 initiates TH2 responses and IgE isotype class switching, whereas IL-5 and IL-13 are important for eosinophil infiltration/activation and increased airway hyperreactivity in allergic asthma." (PMID 29696026, 2018). "Since IFN-γ exerts a direct inhibitory effect on Th2 cytokines and reduces IL-4 and IL-5 production levels, IFN-γ secreted from Th1 cells inhibits the Th2 response leading to allergic disease." (PMID 30545126, 2018). "ILC2, mirroring Th2 cells, express GATA3, secrete IL4, IL5, IL9, and IL13 and are involved in protection against helminthes and in allergic reactions." (PMID 29081776, 2017). "Induction of allergy in the lungs via HDM resulted in an increase in mRNA for IL‐4, IL‐5, IL‐13 and IL‐17." (PMID 27059010, 2016). "Antagonists of IL-5 and CCR3 have been found to have marked potential for inhibition of eosinophil recruitment in allergic diseases." (PMID 27275740, 2016). "IL-1, IL-6 and TNF-α are the main Th1-type cytokines associated with dry eye syndrome, while the inflammatory Th2-type cytokines IL-4, IL-5 and IFN-γ tend to be increased in allergic diseases." (PMID 26588473, 2015). "The IL-5 gene is expressed in CD4+ T-cells, masT-cells, and eosinophils, and in allergic reactions the expression level of the IL-5 gene can be varied." (PMID 24764725, 2014). "In splenocyte cultures, BM4 treatment led to the induction of the allergy-suppressing cytokines IL-10 and IFN-γ, accompanied by a suppression of IL-5 and IL-13 levels." (PMID 24175303, 2013). "Recent work shows the presence of a local allergy reaction in acute phlegmonous appendicitis (APA), with an elevation of Th2 cytokines IL-4, IL-5, and IL-9 in appendicular lavage fluid (ALF), a new concept for evaluating the local immune response in AA developed by our group." (PMID 41596388, 2026). "If AA is a type I hypersensitivity allergic reaction, we would therefore expect that Th2 cells, eosinophils, basophils, IL-4, IL-5, IL-13, and IgE blood concentrations rise in APA, but not in AGA or the appendectomy negative group." (PMID 41596388, 2026). "Currently available IL-4-, IL-5-, and IL-13-targeted therapies underscore the translational gap between the established indication in allergic diseases and the lack of clinical evidence in obesity." (PMID 41007770, 2025).
Allergy (continued). "Collectively, these data show that sia-rDer p 2 inhibits TH2 cytokine production, especially IL-5, and may therefore be a good candidate for Der p 2–specific AIT or be used for prophylactic vaccination against Der p 2–HDM allergy." (PMID 38187864, 2024). "In turn, the histamine increases the secretion of Th2 cytokines such as IL-4, IL-5, and IL-13 and inhibits the production of the Th1 cytokines IL-2 and IFN-γ through the upregulation of prostaglandin E2 and nitric oxide, thereby exacerbating the allergy." (PMID 39403377, 2024). "Elevated IL-5 and parasite-specific cytokines; no alteration in allergen-specific reactivity during peak allergy symptoms." (PMID 39204303, 2024). "We have not previously measured IL-5 when testing the SMAs in allergy models but ES-62 has previously been shown to reduce mRNA levels in draining lymph nodes in the acute OVA model." (PMID 38077318, 2023). "The results showed that hydrogen inhalation significantly alleviated the symptoms of sneezing and pruritus, reduced the infiltration of inflammatory cells into the mucosa, and decreased the levels of IL-5, IL-13, and MCP-1 in serum, indicating the value of hydrogen in treating allergic diseases." (PMID 37007020, 2023). "In the intracavitary space, cytokines such as IL-4 and IL-5 that are elevated in MPE and are central to the allergy cascade and may provide additional targets of therapy." (PMID 35222439, 2022). "These patients did not have a history of allergy and had more severe clinical symptoms and excessive secretion of IL-4 and IL-5 and overdifferentiation of Th0 cells into Th2 cells." (PMID 35531287, 2022). "An important issue that needs to be emphasized considering in vitro tests is the fact that cytokines are determined in various conditions and various diseases; however, only certain cytokines (i.e., TNF-α, IL-2, IL-4, IL-5, IL-6, IL-10, IL-13, and IFN-γ) are important in allergic reactions." (PMID 36590449, 2022). "In terms of eosinophil, it is known to be regulated by IL-5 and eotaxin rather than neutrophils, lymphocytes, and macrophages in allergic diseases." (PMID 36578435, 2022). "Repetitive exposure to ODE did not induce an increase in the Th2 cytokines IL-4, IL-5, and IL-13 which are known to be involved in the classical allergy response and agrees with the lack of MyD88 involvement in regulating serum IgE levels." (PMID 32321514, 2020). "In addition, animal studies have demonstrated that lactic acid bacteria can induce the production of IL-12 and IFN-γ, reduce the production of IL -4, IL-5 and IL-3, promote the immune response of TH1 and inhibit the occurrence of allergic reactions." (PMID 32358397, 2020). "In line with the protective effects that were observed on acute allergic symptoms and IgE, histone acetylation of Th2-related genes (GATA3, IL-4, IL-5, and IL-13) of splenocyte-derived CD4+ T cells after allergy induction was lower in raw milk-treated mice than in shop milk-treated mice." (PMID 31349704, 2019). "Overall, T cell responses from peanut allergics showed a higher IL-5:IFNγ ratio compared to non-allergics, consistent with studies in other allergy systems." (PMID 30304054, 2018). "Many patients, including those with parasitic infection have continued production of IL-5, which does not enhance autoimmunity or allergic diseases." (PMID 29163523, 2017). "We identified seven cytokines from previous glioma or allergy literature (IL4, IL13, IL5, IL6, IL10, IFNG and TGFB2) to determine whether, they were associated with glioma before diagnosis." (PMID 26352148, 2015). "The increase of TH2/TH1 ratio and the IL-5 and IL-13 levels in the BALF of rats that were sensitized with PCGs (GG and GP groups) suggest that the sensitization step was an important factor in the allergic reaction." (PMID 23283149, 2009).
Allergy (continued). "Based on their experiences to date, most participants in this survey believe that anti-interleukin (IL)-5/IL-5Rα biologics are quite effective for most patients with SA, probably owing to the fact that in adult patients with uncontrolled SA, allergy is not the primary pathophysiologic mechanism." (PMID 34185809, 2021). "In the present study, similar downregulation of CD4 T cell responses was observed in mouse allergy among ENA laboratory animal-care workers ARE to mouse allergen, as evidenced by a decrease both in proportion of activated 4-1BB+OX40+ CD4 T cells and in IFN-γ and IL-5 cytokine production." (PMID 33616085, 2021). "In the context of IgE-mediated allergy, activated MCs have been reported to induce an increase in infiltrating neutrophils, which respond to local cytokines by presenting antigen to specific CD4+ effector T-cells that release IL-5 to activate eosinophils and increase the synthesis of IgE." (PMID 32958528, 2020). "Furthermore, atopy/allergy is seemingly rare among APS1/APECED patients, although whether anti-IL5 antibodies underpin this requires more study." (PMID 27426947, 2016). "Additionally, we did not assess IL-5 production, another crucial cytokine related to allergies." (PMID 38538762, 2024). "However, our findings that NK-4 inhibited IL-4 and IL-5 secretion by Th2 cells through down-regulating GATA-3 and NFATc1 mRNA expression suggest that NK-4 could be an effective strategy for the treatment of Th2-mediated allergic disease." (PMID 29933387, 2018). "Interestingly, in mice that constitutively overexpress IL-5 (IL-5Tg/Tg mice) TLR7 expression was significantly reduced and was associated with accumulation of eosinophils in the airways in the absence of allergy." (PMID 26108570, 2015). "In this group, 9 (21%) subjects were considered to have non-allergic asthma in the standard allergy work-up, including SPT and serum IgE.8 patients (19%) who still would not qualify for anti-IgE, anti-IL4, or anti-IL5 treatment." (PMID 36294955, 2022). "In patients with allergies, some studies showed that, in BALF, IL-5 and IL-13, but not IL-4, levels increased when compared with those of healthy patients." (PMID 23283149, 2009). "Important for the context of allergic diseases is the fact, that CD38+ CD4+ T cells were characterized to be hypo-proliferative with a specific bias towards IL-13 secretion (with no change toward IL-4 or IL-5 secretion)." (PMID 38318168, 2024). "Our findings now highlight the potential importance of IL-5 in CAD, especially as the IL-5 receptor is already a viable therapeutic target in allergic diseases, although we can not rule out the possibility that another gene at this locus may be mediating the association with CAD risk." (PMID 21966275, 2011).
allergic asthma (202 papers, 2005 to 2025). A asthma with a basis in a pathological type I hypersensitivity reaction. "This process promotes T-cell proliferation, cytokine secretion (such as IL-4, IL-5, and IL-13), mucus production, and airway remodeling—all hallmark features of allergic asthma." (PMID 40724678, 2025). "Both subsets are highly proinflammatory and express various inflammatory cytokines and mediators such as Il4, Il5, Il13, Tnfsf11, Areg, Tgfb1, Calca and Furin, all of which are implicated in promoting allergic asthma and other allergic diseases." (PMID 40089475, 2025). "Although TNF-α levels remained unchanged, Th2 cytokines associated with allergic asthma (i.e. IL-4, IL-5, and IL-13) were substantially reduced in BALF following ITIH4 administration (p < 0.05)." (PMID 40410722, 2025). "Th2 cytokines—including IL-4, IL-5, and IL-13—are strongly linked to mucus production and airway inflammation, playing vital roles in the development and progression of allergic asthma." (PMID 39806495, 2025). "Pathogenic T helper type 2 cells (pTh2) are involved in allergic asthma and secrete high levels of IL-5 and IL-13." (PMID 40089475, 2025). "The levels of Th2-associated cytokines (IL-4, IL-5, and IL-13) increased in various allergic asthma models; MSC treatments generally restored the Th1/Th2 balance and reduced the cytokine levels, as we also observed." (PMID 35835804, 2022). "The majority of patients with allergic asthma suffer from a type 2 immune response, which is associated with Th2-mediated cytokines, including IL-4, IL-5, IL-9 and IL-13." (PMID 35744915, 2022). "These behavioral and neuroimmune changes in offspring occur in response to allergic asthma-associated elevations in inflammatory cytokines in the dams—namely, IL-4, IL-5, IL-6, and IL-17 —and closely mirror observations reported in clinical settings." (PMID 36009104, 2022). "Maternal serum in the MAA dams showed elevated levels of the T-helper type 2 allergic asthma-associated cytokines, including IL-4 (p = 0.019), IL-5 (p = 0.0004), and IL-13 (p = 0.003), confirming an allergic asthma response." (PMID 36009104, 2022). "The most important cytokines associated with allergic asthma are IL-4, IL-13 and IL-5, that are related to the activity of immune cells such as T cells, B cells producing specific IgE antibodies, eosinophils and mast cells." (PMID 34946286, 2021). "Eosinophils have been associated with Th2 cytokines in allergic asthma; Th2 cytokines (IL-5 and IL-13) have been shown to induce eosinophilic inflammation of the airway." (PMID 30823378, 2019). "T helper type 2-associated cytokines IL-4, IL-5 and IL-13 are involved in the pathogenesis of the eosinophilic airway diseases such as allergic asthma, allergic rhinitis and NP." (PMID 30519393, 2018). "This article discusses the different roles of the IgE and IL-5/eosinophil pathways in the pathogenic mechanisms of airway inflammation occurring in allergic asthma, and the possible reasons to choose an anti-IgE mAb or anti-IL-5 treatment." (PMID 29879991, 2018). "Group 2 innate lymphoid cells (ILC2) are implicated in allergic asthma as an early innate source of the type 2 cytokines IL-5 and IL-13." (PMID 29250067, 2017). "Secretion of both IL-5 and IL-17A is elevated in allergic asthma which is associated with eosinophilic and neutrophilic endotypes, respectively." (PMID 29228740, 2017). "Allergic asthma is a T helper 2 cell (Th2)-mediated disease, in which Th2 cytokines interleukin (IL)-4, IL-5, and IL-13 are closely associated with the symptoms." (PMID 26965110, 2016). "IL-5 generated from Th2 cells attracts and activates eosinophils, which are implicated in tissue destruction in allergic asthma." (PMID 24982682, 2014). "The EPHX1 Y113H and IL5 C-703T SNPs had a moderate antagonistic effect on the allergic asthma risk in women." (PMID 24895604, 2014). "IL-5 has been shown to attract and activate eosinophils, which were implicated in tissue destruction in allergic asthma." (PMID 23731974, 2013).